S100A12 (S100 calcium binding protein A12)
Diseases named in the same sentence as S100A12 in open-access papers (continued):
Sharing a sentence is not in itself a finding about the gene and the disease.
thyroid cancer (3 papers, 2020 to 2025). "Contrary to previous research findings, our MR analysis indicates that genetically predicted circulating S100A12 serves as a protective factor against thyroid cancer." (PMID 40072746, 2025). "Most of the genes showed the same trend as transcriptomics, and in particular, CD177, HSPA1A, HSP1B, and S100A12 were significantly increased in advanced thyroid cancer compared to in indolent thyroid cancer." (PMID 38719807, 2024). "Additionally, there was a notable association between levels of FGF19, IL2RB, TNFRSF9, S100-A12, FLT3LG, and CCL19 and a decreased risk of thyroid cancer." (PMID 40072746, 2025). "The results herein suggest that the S100A12-related G1/S transition may be involved in the inhibitory effect of S100A12 on the development of thyroid cancer." (PMID 32015423, 2020). "In general, this study is the first to investigate S100A12 expression in thyroid cancer." (PMID 32015423, 2020). "Downregulation of S100A12 could inhibit the growth of thyroid cancer." (PMID 32015423, 2020). "To discover the potential signaling pathway contributing to the regulatory role of S100A12 in thyroid cell progression, we examined the levels of phosphorylated ERK and total ERK in both thyroid cancer cell lines." (PMID 32015423, 2020). "However, the function of S100A12 in thyroid carcinoma has not yet been investigated." (PMID 32015423, 2020).
acne (2 papers, 2021 to 2024). An inflammatory process of the sebaceous glands which is characterized by comedones, nodules, papules and/or pustules on the skin. "It was demonstrated by microarray and experimental methods that TCN1 and S100A12 may affect the disease process of acne by participating in the innate immune and cellular differentiation processes of hair follicles and epidermal keratin-forming cells." (PMID 35047008, 2021).
acute pancreatitis (2 papers, 2022 to 2024). An acute inflammatory process that leads to necrosis of the pancreatic parenchyma. "As supported by previous studies, genes like S100A12, S100A9 and IL-1B hold substantial value as markers for predicting the severity of Acute Pancreatitis, in line with our research results." (PMID 39372399, 2024).
atrial fibrillation (2 papers, 2024). A disorder characterized by an electrocardiographic finding of a supraventricular arrhythmia characterized by the replacement of consistent P waves by rapid oscillations or fibrillatory waves that vary in size, shape and timing and are accompanied by an irregular ventricular response. "The intermediary molecule, taurocholic acid sulfate, linked to S100-A12, also correlates with an increased risk of atrial fibrillation, further confirming the close relationship between ED and cardiovascular diseases." (PMID 38827362, 2024).
autoimmune uveitis (2 papers, 2016 to 2023). An autoimmune form of uveitis (disease). "Moreover, IL-8, sICAM-1, and S100A12 have also been seen as potential biomarkers for JIA-associated autoimmune uveitis." (PMID 36969183, 2023). "Increased S100A8/A9 and S100A12 levels are found in the serum and aqueous humor of patients with autoimmune uveitis, and authors indicated that the serum levels reflect activity of joint and eye disease." (PMID 27786310, 2016).
chronic heart failure (2 papers, 2017 to 2024). "In chronic heart failure, plasma level of S100A12 was significantly elevated." (PMID 28771541, 2017).
co-infection (2 papers, 2021 to 2025). "Our multicohort analysis established an NB-based diagnostic model utilizing S100A12/S100A8, which maintains diagnostic accuracy across diverse geographic, ethnic, and clinical variables (including HIV co-infection), highlighting its potential for clinical translation in LTBI/ATB differentiation." (PMID 40415930, 2025). "For patients at tier 1 severity level, they did not have significantly different S100A12 expression compared to the controls unless they had confirmed bacterial co-infection." (PMID 34108608, 2021).
coronary atherosclerosis (2 papers, 2019 to 2025). Atherosclerosis of the coronary vasculature. "The relationship between S100A12 and coronary atherosclerosis has been mentioned in previous studies." (PMID 40269701, 2025). "In conclusion, the plasma levels of sRAGE and S100A12 were increased in patients with ACS; however, these did not change significantly in patients with stable angina and nonstenosis coronary atherosclerosis." (PMID 31275446, 2019).
delirium (2 papers, 2019 to 2023). A disorder characterized by confusion; inattentiveness; disorientation; illusions; hallucinations; agitation; and in some instances autonomic nervous system overactivity. "However, circulating S100A12 levels are not investigated in patients with delirium or cognitive dysfunction." (PMID 30548434, 2019).
depression (2 papers, 2022 to 2025). "Finally, we identified ARG1, TPST1 and F5 as core genes associated with S100A12 expression in depression." (PMID 36325528, 2022). "Subsequently, ROC analysis of the GSE22132 dataset revealed that S100A12 may be the most potential diagnostic marker in peripheral blood for depression." (PMID 36325528, 2022). "Consistent with this study, S100A12 is reported to be most clinically diagnosable biomarker upregulated in depression based on machine learning algorithms, whereas, which was found upregulated in blood and downregulated in tissues of IPF patients." (PMID 40655156, 2025). "ROC analysis based on both GSE98793 and GSE76826 datasets suggested that S100A12, TIGIT, SERPINB2, GRB10, and LHFPL2 in the peripheral serum have the potential to act as diagnostic biomarkers for depression." (PMID 36325528, 2022). "The genes S100A12, TIGIT, SERPINB2, GRB10, and LHFPL2 in peripheral serum are viable diagnostic biomarkers for depression." (PMID 36325528, 2022). "Subsequently, S100A12, TIGIT, SERPINB2, GRB10, and LHFPL2 in peripheral blood were identified as Potential diagnostic biomarkers in peripheral blood for depression by SVM–REF, Random forest, and LASSO algorithms." (PMID 36325528, 2022). "S100A12, TIGIT, SERPINB2, GRB10, and LHFPL2 identified as potential diagnostic biomarkers in peripheral blood of patients with depression using three machine learning algorithms." (PMID 36325528, 2022). "In the present study, decreased BDNF was also found in the hippocampal region of mice induced by BLM, which suggested that S100A12 may affect depression by influencing neuroinflammation and related pathways." (PMID 40655156, 2025). "The functional analysis of gene modules related to S100A12 also indicated that it may be involved in the immune regulatory response in depression, and the core genes of ARG1, TPST1 and F5 related to its expression were found." (PMID 36325528, 2022). "Based on the results of the ROC (validation set AUC value > 0.7) analysis in the current study, S100A12, TIGIT, SERPINB2, GRB10, and LHFPL2 may possess potential as diagnostic biomarkers of depression." (PMID 36325528, 2022). "Among them, the relevance scores of S100A12, TIGIT, SERPINB2, GRB10, and LHFPL2 with depression were 4.356, 4.232, 3.064, 1.516, and 0.698, respectively." (PMID 36325528, 2022). "We further investigated the role of S100A12, TIGIT, SERPINB2, GRB10, and LHFPL2 in depression and observed their expression profiles in patients." (PMID 36325528, 2022). "Subsequently, the genes S100A12, SERPINB2, TIGIT, GRB10, and LHFPL2 in peripheral serum were identified as depression biomarkers by using machine learning algorithms." (PMID 36325528, 2022). "No studies have reported a direct association of S100A12, TIGIT, SERPINB2, GRB10, and LHFPL2 with depression." (PMID 36325528, 2022). "Finally, the results from the three algorithms were combined, yielding S100A12, TIGIT, SERPINB2, GRB10, and LHFPL2 in peripheral blood as depression-related potential biomarkers." (PMID 36325528, 2022).
dermatomyositis (2 papers, 2021 to 2023). Dermatomyositis (DM) is a type of idiopathic inflammatory myopathy characterized by evocative skin lesions and symmetrical proximal muscle weakness. "Enriched genes including S100A12, MPO (myeloperoxidase), S100A8, CXCL10, S100A9, CD244, CD244,and TLR7 have been linked to dermatomyositis." (PMID 38137330, 2023).
diabetic neuropathy (2 papers, 2017 to 2024). A chronic, pathological complication associated with diabetes mellitus, where nerve damages are incurred due to diabetic microvascular injury involving small blood vessels that supply these nerves, resulting in peripheral and/or autonomic nerve dysfunction. "For example, CCL2, S100A12, and matrix metalloproteinases are elevated in conditions like diabetic neuropathy, trigeminal neuralgia, and compressive radiculopathies." (PMID 39015317, 2024).
dyslipidemia (2 papers, 2023 to 2025). "In conclusion, elevated S100A12 level is an independent risk factor for PAD in patients with dyslipidemia." (PMID 40269701, 2025). "Firstly, this study for the first time found a significant correlation between S100A12 and the risk of PAD among patients with dyslipidemia, confirming that S100A12 plays an important role in the atherosclerotic process of peripheral arteries induced by LDL-C." (PMID 40269701, 2025). "This study aims to investigate the association between S100A12 and the risk of PAD in patients with dyslipidemia." (PMID 40269701, 2025). "This study, for the first time, showed a positive correlation between S100A12 and PAD risk among patients with dyslipidemia." (PMID 40269701, 2025). "Levels of S100A12 were significantly higher in the PAD group of dyslipidemia [0.22 (0.13,1.49) ng/cL vs. 0.13 (0.10,0.18)ng/cL, p value < 0.001]." (PMID 40269701, 2025). "The present study focused on the patients with dyslipidemia, suggesting that S100A12 may play a broader role in PAD." (PMID 40269701, 2025). "The correlation between S100A12 and PAD risk in patients with dyslipidemia is still unclear." (PMID 40269701, 2025). "Interestingly, the present study found that S100A12 was significantly elevated in dyslipidemia PAD patients, but S100A8/A9, also as calcium-binding proteins which was reported to act an important role in oxidative stress, was not significantly elevated in these patients (p value = 0.069)." (PMID 40269701, 2025).
eosinophilia (2 papers, 2013 to 2025). "The top proteins with the largest log2 fold change in this group included IL-19, STAT5B, CCL17, S100A12, and CCL22—inflammatory mediators known to be associated with AD inflammation and eosinophilia." (PMID 41357518, 2025).
familial hypercholesterolemia (2 papers, 2022 to 2023). An inheritable form of hyperlipidemia, in which there are excess lipids in the blood. "S100A12 level is increased in patients with familial hypercholesterolemia and may contribute to a better assessment of cardiovascular risk profile." (PMID 37217870, 2023).
injury (2 papers, 2019). Damage inflicted on the body as the direct or indirect result of an external force, with or without disruption of structural continuity. "sRAGE and S100A12, biomarkers associated with lung injury, were found to be highly concentrated in pulmonary tissue and bronchoalveolar lavage fluid in acute lung injury and have been known to predict acute lung injury after surgery." (PMID 31740727, 2019). "A previous clinical study has demonstrated that circulating S100A12 levels were correlated with C‐reactive protein level in peripheral blood derived from patients with severe traumatic brain injury, indicating that S100A12 might be involved in inflammation after brain injury." (PMID 30548434, 2019).
leukocytosis (2 papers, 2022 to 2023). "Cats with leukocytosis had higher duodenal/proximal jejunal numbers of S100A8/A9+ (median: 8.5 vs. 4; p = 0.012) and S100A12+ cells (median: 6.5 vs. 3; p = 0.014) than cats with normal peripheral leukocyte counts." (PMID 36009635, 2022).
metastatic disease (2 papers, 2021 to 2023). "Taken together this suggests that S100A9 and S100A12 levels in blood could be markers of metastatic disease." (PMID 34067757, 2021). "A possible association of metastatic disease with S100A8/A9+ cell counts, S100A12+ cell counts, or Cal-ratios could not be evaluated due to most dogs (8/9, 89%) having suspected or confirmed metastatic disease at the time when prostatic neoplasia was diagnosed." (PMID 37946179, 2023).
Onset (2 papers, 2017 to 2020). The age group in which disease manifestations appear. "Massively increased (100-fold) S100A12 serum concentrations during and between attacks are suggested to be very specific for FMF and systemic-onset JIA, which may help diagnose and monitor inflammatory activity." (PMID 32806879, 2020).
osteoarthritis (2 papers, 2014 to 2022). A noninflammatory degenerative joint disease occurring chiefly in older persons, characterized by degeneration of the articular cartilage, hypertrophy of bone at the margins and changes in the synovial membrane. "In RA and osteoarthritis patients, three S100 proteins, including S100A8, S100A9, and S100A12 are the most up-regulated biomarkers." (PMID 35796625, 2022). "Additionally, using a SELDI approach, other groups found the S100A8 and S100A12 (Calgranulin C, MRP6) proteins as markers able to differentiate RA from osteoarthritis." (PMID 25546405, 2014).
parasitic infection (2 papers, 2017 to 2023). "Although there is inadequate information on the function of S100A12 in parasitic infection in livestock, it is known to be highly expressed in bacterial infection in humans." (PMID 37761803, 2023).
pyometra (2 papers, 2015 to 2020). "In line with our findings, a marked upregulation of S100A12 gene expression in the uterus of bitches with canine pyometra in comparison to healthy controls has been reported." (PMID 32596263, 2020). "Overexpression of S100A8, S100A9 and S100A12 genes were detected in pyometra, particularly in the hormone-treated animals." (PMID 26222498, 2015). "S100A12, vimentin, and Hp were the proteins most up-regulated in canine pyometra." (PMID 32596263, 2020).
steatosis (2 papers, 2025). Increased lipid within the cytoplasm of cells. "Steatosis severity was associated with upregulation of COL5A3 and TP53I3, whereas upregulated RASGEF1B, S100A12, and TGFBR3 were linked to early-stage liver steatosis." (PMID 40689242, 2025). "Interestingly, in our study, liver expression of MDSC markers S100A8/S100A9/S100A12 was positively correlated with ATI, a measure of steatosis." (PMID 40257301, 2025).
systemic sclerosis (2 papers, 2019 to 2022). A chronic disorder, possibly autoimmune, marked by excessive production of collagen which results in hardening and thickening of body tissues. "Infact, among S100 A proteins, S100A7, S100A8, S100A9, S100A12 have been already described as differentially expressed in other systemic autoimmune diseases and particularly in Systemic Sclerosis." (PMID 31249499, 2019). "In addition, lung S100A12 was significantly downregulated in patients with non-specific interstitial pneumonia (NSIP), systemic sclerosis-related ILD (SSc-ILD), and respiratory bronchiolitis-related ILD (RB-ILD) compared with control participants." (PMID 35185901, 2022).
Acute hepatitis (1 paper, 2020). Acute hepatic injury resulting from inflammation typically accompanied by increased serum alanine transaminase activity. "Higher expression of S100A8 during acute hepatitis in both trimesters and additionally S100A12 in the third trimester, with normal expression of S100A9 suggests similar role in the PR patients as well." (PMID 32012176, 2020).
acute leukemia (1 paper, 2014). A clonal (malignant) hematopoietic disorder with an acute onset, affecting the bone marrow and the peripheral blood. "As this step marks the transition to an acute leukemia, the overlapping genes (CEBPB, FOS, FOSB, IL8, S100A12, SOCS2) might be involved in the aggressiveness of MLL-AF9 myeloid leukemia blasts." (PMID 24517546, 2014).
AIDS (1 paper, 2020). A syndrome resulting from the acquired deficiency of cellular immunity caused by the human immunodeficiency virus (HIV). "We assessed the distribution of S100A8/9 and S100A12 with regard to disease activity in the AIDS+SURFS group." (PMID 31948488, 2020).
Allergy (1 paper, 2025). An allergy is an immune response or reaction to substances that are usually not harmful. "Levels of tumor necrosis factor ligand superfamily member 14 (TNFSF14) and protein S100-A12 (EN-RAGE) increased over visits in both allergy groups." (PMID 40929127, 2025).
anaphylaxis (1 paper, 2023). An acute hypersensitivity reaction that occurs from exposure to an allergen. "Taking the intersection of six algorithms (DMNC, Stress, MCC, Degree, Closeness, Radiality) in cytoHubba, we found 6 hub genes shared by anaphylaxis and STEMI: IL1R2, S100A12, FOS, MMP9, DUSP1, and CLEC4D." (PMID 37469874, 2023).
aneurysm (1 paper, 2016). Bulging or ballooning in an area of an artery secondary to arterial wall weakening. "In addition, S100A12, another DAMP molecule recently recognized as a common ligand of RAGE and TLR4, has been associated with production of IL-6 and MMP-2 and enhancement of aneurysm formation." (PMID 26741694, 2016). "Studies have shown that HMGB1 and S100A12, another recently recognized TLR4 ligand, contribute to vascular inflammation and MMP production, implicating a role of TLR4 in aneurysm lesions." (PMID 26741694, 2016). "Due to absence of the human DAMP molecule S100A12 in mice, the VSMC-specific S100A12 transgenic mice are generated to investigate the role of S100A12 in aneurysm formation." (PMID 26741694, 2016).
aortic atherosclerosis (1 paper, 2017). A atherosclerosis that involves the aorta. "Apart from pentosidine and LMW AGEs, the AGE receptor is also activated by S100A12/ENRAGE, an important ligand for this receptor that has been implicated in vascular inflammation, coronary and aortic atherosclerosis, and plaque vulnerability and in human cardiovascular disease." (PMID 29362665, 2017).
Arrhythmia (1 paper, 2024). Any cardiac rhythm other than the normal sinus rhythm. "The role of S100A12 in arrhythmias, however, remains less clear, with further exploration needed to understand its relationship with arrhythmia fully." (PMID 39444551, 2024).
autoinflammatory syndrome (1 paper, 2020). A group of disorders of the innate immune system characterized by attacks of seemingly unprovoked inflammation without significant levels of either autoantibodies or autoreactive T cells more characteristic of autoimmune disease. "Levels of S100A8/9 and S100A12 are an indicators of disease activity in sJIA but not in other autoinflammatory syndromes or nsJIA." (PMID 31948488, 2020).
bacterial pneumonia (1 paper, 2021). Acute infection of the lung parenchyma caused by bacteria (e.g., Streptococcus pneumoniae, Haemophilus influenzae, Chlamydia pneumoniae, Mycoplasma pneumoniae, and Legionella pneumophila). "Compared to the control group at both time points, the patients with severe bacterial pneumonia had significantly elevated S100A12 expression at day one (p = 5.74e-13 and 1.79e-12)." (PMID 34108608, 2021).
bacterial sepsis (1 paper, 2023). "Overall, among ICU patients, S100A12 activation could be even stronger in certain patients within the negative groups (such as bacterial sepsis), while IFI27 activation was more restricted to the positive group." (PMID 36649304, 2023).
bipolar disorder (1 paper, 2022). A disorder of the brain that causes unusual shifts in mood, energy, activity levels and the ability to carry out day-to-day tasks. "A transcriptomic analysis of the dorsal striatum comparing individuals with bipolar disorder and controls found significant changes in the expression of 14 genes, including a few immune response genes, such as NLRC5, S100A12, LILRA4, and FCGB27." (PMID 36371440, 2022).